IL6 (interleukin 6)
Diseases named in the same sentence as IL6 in open-access papers (continued):
Sharing a sentence is not in itself a finding about the gene and the disease.
Sepsis (continued). "In summary, the combination of IL-6, NT-proBNP, and INR may serve as a potential predictor of 28-day mortality in critically ill patients with sepsis or septic shock." (PMID 33446739, 2021). "Besides, the injection of miR-378a-3p antagomir hindered the inflammatory response augment induced by sepsis, presenting as the downregulation in TNF-α, IL-1β, IL-6 (P < 0.05)." (PMID 34565302, 2021). "In addition, serum cytokine levels of IL-1β, IL-6, IL-8, IL-10, IL-12, IL-17A, IL-18, IFN-γ, TNF-α, and calprotectin were found to be elevated in sepsis." (PMID 34654467, 2021). "In addition, STS has been shown to suppress the release of IL-6 and TNF-α in a mouse model of sepsis." (PMID 34122723, 2021). "An in vivo study involving an LPS-stimulated mouse model of sepsis reported reduced levels of inflammatory mediators (TNF-α, IL-1β, and IL-6) and an elevated level of the anti-inflammatory cytokine IL-10 in septic mice fed with lyophilized powder of wild bitter gourd-supplemented diet." (PMID 33193799, 2020). "MAPK signaling is suppressed by blocking the phosphorylation of JNK and p38, which decreases the levels of the pro-inflammatory cytokines IL-6 and TNF-α and increases the level of the anti-inflammatory cytokine IL-10 to subsequently alleviate the inflammation in subjects with sepsis-induced ARDS." (PMID 32319516, 2020). "Delivery of NaHS to sepsis-induced mice leads to a marked increase in lung pro-inflammatory cytokines TNF-α, IL-1β, IL-6, chemokines MIP-1α and MIP-2, and adhesion molecules P-selectin, E-selectin, VCAM-1, and ICAM-1 which affect inflammation and immune cell migration." (PMID 33330130, 2020). "Moreover, the protective effect of PD against the sepsis-induced increase in serum cytokines, including TNF-α, IL-1β, and IL-6, was inhibited by mdivi-1 treatment." (PMID 32131850, 2020). "In contrast, sepsis was not present in the CoPP-treated rats, with significantly lower serum IL-6 and IFN-γ." (PMID 32015027, 2020). "During sepsis, the “cytokine storm” mediates the initial pro-inflammatory phase by releasing proinflammatory cytokines, such as IL-1α, IL-1β, tumor necrosis factor-α (TNF-α), IL-6, and interferon gamma (IFN-γ), among others." (PMID 32630422, 2020). "Elevated plasma concentrations of IL-10, IFN-γ, IP-10, IL-12p70, IL-6 and CCL2, were strongly associated with confirmed LOS compared to no LOS; consistent with other preterm infant sepsis studies." (PMID 32407417, 2020). "The results of studies assessing the prognostic value of interleukin-6 are not conclusive but indicate its potential usefulness as a prognostic marker in sepsis." (PMID 32655314, 2020). "Sepsis is a systemic inflammatory reaction syndrome, accompanied by acute inflammatory responses, with the release of multiple inflammatory factors such as TNF-α and IL-6." (PMID 32188465, 2020). "In addition, an increase in IL-6 levels and a decrease in CRP levels were detected with increasing PMI (post-mortem interval) in sepsis cases." (PMID 33092081, 2020). "The levels of diaphragmatic TNF-α, IL-1β, and IL-6 were increased significantly in rats in the sepsis group compared to rats in the sham group 24 h after surgery (P < 0.01), while TNF-α, IL-1β, and IL-6 concentrations at 24 h after CLP were reduced after NRG-1β treatment (P < 0.01)." (PMID 32765805, 2020). "IL-6, IL-1β and TNF-α are among the major cytokines responsible for sepsis disease pathogenesis." (PMID 32117233, 2020). "Further evidence has suggested that overexpressed IL-6 and TNF-α by systematic immune responses might support a vital role in the development of myocardial malfunction in sepsis." (PMID 32423469, 2020). "Accordingly, in contrast with inflammatory cytokines such as IL-1β, IL-6, TNF-α, and IFN-γ, elevation of IL-18 has levels been reported to be characteristic of AOSD and, thus, potentially useful for differentiating AOSD from sepsis." (PMID 32381117, 2020).
Sepsis (continued). "IL-6 in mouse serum was 10~20 pg/ml at 24 h and 48 h in both stages of sepsis, but its level did not change in PDK1 deletion mice in the late stage." (PMID 32774145, 2020). "In another study using a murine sepsis model, the pharmacological blocking of adrenergic β-receptors led to an inhibition of the proliferation as well as an increased apoptosis rate of splenocytes and a varied release of cytokines (IFN-γ, IL-6)." (PMID 32708472, 2020). "Herein, CRP and IL-6 levels were significantly higher in patients with sepsis than in those without sepsis at hospital admission." (PMID 33178716, 2020). "Increased Il6 and MMP9 levels are well described in inflammation and during sepsis." (PMID 33178198, 2020). "Furthermore, prolactin administration profoundly affected cellular cytokine release (IL-2, IL-6, IFN-γ) 48 h after induction of sepsis by cecal ligation and puncture." (PMID 32708472, 2020). "IL-2, IL-6, IL-10, and NLR were significant after univariate regression analysis, but they were not independent risk factors for sepsis in our study." (PMID 32802049, 2020). "However, a study conducted by Jedynak and co-workers suggested that sTREM-1 was outperformed by both CRP and IL-6 for the diagnosis of severe sepsis and septic shock, although sTREM-1 did outperform PCT for the diagnosis of severe sepsis." (PMID 32164268, 2020). "The results showed high levels of proinflammatory cytokines TNF-α and IL-6 in BALF of sepsis mice without b-AP15 treatment when compared with controls." (PMID 32391376, 2020). "Two studies investigated the use of IL-6 along with PCT and CRP for the diagnosis of sepsis." (PMID 32164268, 2020). "In accordance, IL‐6 plasma levels were lower after pemafibrate treatment compared with vehicle‐treated controls 24 h after CLP, indicating a more controlled inflammatory environment during pemafibrate‐pretreated sepsis." (PMID 31916705, 2020). "Interleukin-6 (IL-6) and C-reactive protein (CRP) are being used for diagnosis of sepsis." (PMID 33233806, 2020). "Endotoxin-treated animals therefore present a clinical picture that is similar to sepsis with systemic arterial hypotension; impaired myocardial contractility; and increased circulating levels of lactate, tumour necrosis factor (TNF), and interleukin-6 (IL-6)." (PMID 33425215, 2020). "Compared to those of control mice, mRNA levels of the IL-6, IL-10, and CCL3 in peripheral blood mononuclear cells (PBMCs) of septic mice were significantly increased, all of which are known to be key markers of sepsis severity and mortality." (PMID 33182773, 2020). "After treatment with rSj-Cys, the levels of these biochemical markers of cardiac injury were significantly reduced, which was associated with the reduction of inflammatory cell infiltration in the heart and the proinflammatory cytokines (IL-6 and TNF-α) in sepsis mice." (PMID 32423469, 2020). "Noticeably, IL-6 and TNF-α are the primary mediators of local inflammation and sepsis." (PMID 32414062, 2020). "In our sepsis model, the injurious pulmonary inflammatory response is closely related to high levels of inflammatory mediators (TNF-α, IL-1β, and IL-6) found in the septic mesenteric lymph, especially with respect to the effect of the amplified inflammatory cascade response seen in septic syndrome." (PMID 33145344, 2020). "Our results indicate that simvastatin treatment has an important negative immunomodulatory effect in sepsis since it was able to lower the levels of IL-6, TNF-α, IL-1β, and MIF in the peritoneal cavity in our model." (PMID 33110395, 2020). "Studies on both patients with sepsis and sepsis animal model indicated that HMGB1 could facilitate the release of inflammatory cytokines from macrophages, such as: TNF-α, interleukin-6 (IL-6)." (PMID 33552058, 2020). "Furthermore, it downregulated the transcriptions of proinflammatory cytokine IL-6, TNF-α, and Il-1β and upregulated IL-10 transcription in the liver of sepsis mice." (PMID 32457606, 2020).
Sepsis (continued). "However, most common biomarkers for sepsis diagnosis including PCT, CRP, and interleukin 6 have limited specificity and sensitivity." (PMID 32214905, 2020). "The higher IL-6 plasma concentrations in our study are in line with previous studies of preterm infants that showed increased plasma IL-6 concentrations during sepsis compared to non-infected or control groups." (PMID 32479514, 2020). "Consistent with previous studies, elevated cytokine levels were common in the two types of sepsis of our study and there were also differences in the levels of IL-6 and IL-10 between survivors and nonsurvivors of the two sepsis groups." (PMID 33329592, 2020). "In our study, we showed that the hippocampal expressions of IL-1β and IL-6 but not other inflammatory factors were upregulated by sepsis, suggesting IL-1β and IL-6 are specifically affected by CLP." (PMID 33061831, 2020). "Additionally, sepsis-induced lymphocyte depletion was ameliorated, levels of circulating pro-inflammatory cytokines TNF-α and IL-6 were increased, anti-inflammatory IL-10 levels were decreased and bacterial clearance was enhanced." (PMID 33336293, 2020). "In this study, we found that elevations in IL-6, IL-8, IL-10, MCP-1, and PAI-1 serum levels were common features in patients with sepsis, ARDS, or burns and that the serum IL-6 level was positively correlated with the serum levels of other cytokines and of PAI-1 in CRS patients." (PMID 32826331, 2020). "In this study, IL-6 levels in patients with sepsis were significantly higher than those in patients without sepsis." (PMID 32635454, 2020). "Previous studies have clearly indicated the importance of IL-1β, IL-6, IL-10, and TNF-α in sepsis." (PMID 33324396, 2020). "NB 06, like chloroquine, modulates the gene expression of the prominent inflammatory messengers IL-1B, IL-23A, CCL4, CCL20, and IL-6; likewise, it has beneficial effects in (systemic) infections involving bacterial endotoxins, such as LPS, by targeting the TLR4 receptor pathway in sepsis." (PMID 32668803, 2020). "Furthermore, MDSC are induced and activated in the presence of estrogen and cytokines, such as IL-6, IFN-γ and IL-1β, and strongly contribute to T-cell dysfunction in various diseases such as sepsis, tumorigenesis and trauma." (PMID 32708472, 2020). "Similarly, in the cecal ligation and puncture (CLP) sepsis model, PAG treatment reduced mRNA and protein levels of pro-inflammatory cytokines IL-1β, IL-6, TNF-α in mice, indicating that H2S potentiates systemic inflammation in sepsis." (PMID 33330130, 2020). "Our findings imply that STAT3 is critical for the production of different pro-inflammatory mediators, including TNF-α, IL-1β, IL-6, and MCP-1, in CLP-induced sepsis, although STAT3 would work coordinately with other transcriptional co-activators or transcription factors." (PMID 32943679, 2020). "Activated macrophages could produce and release pro-inflammatory cytokines, such as TNF-α, IL-6, NO and PGE2, which thus played a key role in inflammatory diseases such as sepsis, rheumatoid arthritis, inflammatory bowel disease, psoriasis and Type 2 diabetes." (PMID 32031205, 2020). "IL-6 and TNF-α concurrently stimulate the production of C-reactive protein (CRP) and procalcitonin (PCT), which are the most widely used inflammatory biomarkers in patients with sepsis in clinical practice." (PMID 32778146, 2020). "It was found that proinflammatory cytokines, including IL-1β, IL-6, and TNF-α, substantially decreased after EVs were applied to LPS-stimulated macrophages and mice, and thus, LPS induced M1 polarization was inhibited and sepsis was strongly alleviated." (PMID 32719678, 2020). "C-reactive protein (CRP), the clinically most important acute-phase protein, and interleukin-6 (IL-6) are both early biomarkers that can provide valuable information for distinguishing non-microbial SIRS from sepsis." (PMID 32912236, 2020).
Sepsis (continued). "Analysis using Hdc‐deficient mice showed that the increase in TNFα, IL‐1b, IL‐6 and MCP1 levels in sepsis was attenuated when there was a lack of histamine, indicating that the induced histamine promotes the production of the pro‐inflammatory cytokines." (PMID 32394600, 2020). "It remains to be discussed why target attainment did not lead to a significantly faster reduction of interleukin-6, although it is an important parameter to evaluate the success of antibiotic therapy in patients diagnosed with sepsis." (PMID 33292582, 2020). "Also, circC3P1 dramatically attenuated pulmonary injury, decreased pro‐inflammatory cytokines (TNF‐a, IL‐6 and IL‐1β), cell apoptosis and p‐AKT/AKT levels induced by sepsis." (PMID 32846020, 2020). "Plasma hepcidin, EPO and IL-6 of survivor or non-survivor patients with sepsis upon ICU admission were significantly higher than those of healthy volunteers and decreased gradually throughout the study." (PMID 31183575, 2019). "Furthermore, APC increases the survival of patients with sepsis through its anti-inflammatory effect by reducing both NF-κB pathway and expression of pro-inflammatory cytokines such as TNF-α and IL-6 induced by LPS." (PMID 31315617, 2019). "In this study, the results showed that knockdown of miRNA-106a reduced LPS-induced the levels of inflammatory factor TNF-α, IL-1β and IL-6, suggesting that inhibiting the expression of miRNA-106a might inhibit the occurrence of AKI induced by sepsis." (PMID 31432993, 2019). "In all groups, the concentrations of PCT and IL-6 in the sepsis group were higher than those of the noninfection (P < 0.001) and infection groups (P < 0.05; P < 0.001)." (PMID 31915467, 2019). "Furthermore, we demonstrated the inhibitory effects of LDK378 on the sepsis-induced up-expression of TNF-a and IL-6 and the enhanced effects of LDK378 on IL-10 expression in septic rats." (PMID 30820191, 2019). "The disruption of TLR signaling pathway induced by live virulent E. coli and E. coli-derived LPS in pigs by CD14 neutralization antibodies resulted in decreased levels of pro-inflammatory cytokines IL-1β, IL-6, IL-8, and TNF-α, and lower granulocyte activation in a pig model of sepsis." (PMID 31847111, 2019). "While the control samples were negative for anti-IL6 abs, the patient's serum was found positive in time of sepsis as well as 1 month after the infection." (PMID 31781117, 2019). "At the same time, the serum IL-6 and TNF-α levels which are early biomarkers for sepsis also reached a maximum at around 4 h and 2 h after the injection, respectively (p < 0.05), indicating that TSLP may be an early biomarker for sepsis." (PMID 31480519, 2019). "Interestingly, only Olv and Omg decreased the sepsis-induced secretion of the inflammatory cytokines, TNF-α, IL-6, and IL-1β and stimulated the secretion of the anti-inflammatory cytokine, IL-10." (PMID 31333903, 2019). "The results showed that serum IL-6 and PTX3 levels could identify the severity of sepsis (sepsis, septic shock, and controls) with optimal cut-off values." (PMID 31718563, 2019). "As a common life-threatening disease among infants, IL-6 measurement in neonatal sepsis (NS) diagnosing has been shown to serve as an effective, noninvasive, and rapid method." (PMID 31671729, 2019). "Such interactions between IL-6 and HPX may contribute to the worsening of sepsis including the development of septic shock." (PMID 31554244, 2019). "In addition, nutlin-3a significantly decreased IL-6, VEGF, ICAM-1, and CK levels in serum (p < 0.05) and IL-6 and VEGF levels in the liver of mice with sepsis (p < 0.05)." (PMID 31480519, 2019). "For the proinflammatory cytokines, the levels of IL-1β, IL-2, IL-6, and TNF-α were elevated in the early sepsis phase (2 h), but most other proinflammatory cytokines, including IL-12, IL-15, IL-17, and IFN-γ, showed significant elevation in the late sepsis phase (24–48 h)." (PMID 31354717, 2019).
Sepsis (continued). "Likewise, gene expression of these cytokines in gastrocnemius muscle showed that pro-inflammatory IL-6 and TNFα were comparable among NSC and sepsis survivors at 2 weeks (p=0.622 and p=0.565, respectively)." (PMID 31793435, 2019). "In a different report, IL-6 gene expression was significantly increased in non-surviving septic foals compared to foals that survived sepsis." (PMID 30931316, 2019). "Previous studies report an increase in serum concentrations of IL-6 and IL-10 in healthy dogs 3 days after ovariohysterectomy and identified KC-like as being significantly higher in dogs with pyometra and sepsis compared to dogs without sepsis." (PMID 32010716, 2019). "Past statin use may attenuate system inflammations, such as sepsis (TNF-α and IL-6) or acute lung injury, with multiple organ failure as demonstrated in a previous study supporting our result." (PMID 31474854, 2019). "To further determine whether GSS inhibits sepsis-induced lung inflammation in vivo, we use ELISA analysis to check the changes of TNF-α and IL-6 in the lung tissue and serum, respectively." (PMID 32082076, 2019). "Serum levels of TNF-a, IL-6, and IL- 10 at 6 h and 30 h were significantly elevated in CLP-induced sepsis in comparisons with those in the sham group (p < 0.05), serum levels of TNF-a, IL-6, and IL- 10 of LDK378 group at 54 h were higher than sham group (p < 0.05)." (PMID 30820191, 2019). "This mixed early peak in both pro-(IL-6 and TNF) and anti-inflammatory (IL-10) cytokines between time of insult (trauma, hemorrhage, and/or sepsis) and day 1 has been seen in inflammatory stimuli animal models as well as clinical sepsis studies." (PMID 29849508, 2018). "In predicting the development of severe sepsis, the highest AUCs were found for PCT (0.744, 95% CI 0.638–0.85) and sTREM-1 (0.664, 95% CI 0.55–0.778); and in septic shock prediction, for PCT (0.766, 95% CI 0.665–0.867) and IL-6 (0.707, 95% CI 0.595–0.819)." (PMID 29282483, 2018). "Consistently, our data showed that IL-27 treatment significantly enhanced TNF-α and IL-6 secretion and apoptosis of THP-1 cells upon LPS stimulation, which further demonstrated that IL-27 is critical in the pro-inflammatory responses during sepsis." (PMID 30268141, 2018). "This suggests that the cytokine network composed by the pro-inflammatory cytokines IL-6, IL-8 and MCP-1, when interacting with endothelial cells, could facilitate the progression of sepsis based on the coagulation disorder, leading to a lethal outcome." (PMID 30228372, 2018). "We did not confirm associations between levels of pro-inflammatory biomarkers over time, especially IL-6 and IL8, and delirium, even though delirious patients appeared to have more sepsis (46% vs. 20%, p = 0.08), a condition that has been associated with delirium." (PMID 29801516, 2018). "This indicates that endothelial cell injury might play a role in forming the cytokine network composed of IL-6, IL-8 and MCP-1 throughout the acute phase of sepsis." (PMID 30228372, 2018). "Although the test for interleukin-6 (IL-6) is not yet covered, a kit for clinical use has been developed and is currently in use by some medical facilities as part of the management of sepsis." (PMID 29435330, 2018). "Surprisingly, the classical pro-inflammatory cytokines often postulated as important drivers of sepsis, e.g. IL-6, are not regulated in any manner." (PMID 29920518, 2018). "SIRS patients were distinguished from sepsis patients at a DcR3 cutoff of 1.96 ng/ml (a value of 95% CI for SIRS tested) with a sensitivity of 90.77% and a specificity of 98.40%, better than the commonly used biomarkers of PCT, CRP, and IL-6." (PMID 29541387, 2018). "In this study, we showed that GSKJ4 protects mice against septic death and reduces the expression of inflammatory factors IL-1β, TNF-α, IL-6, and MCP-1 in vivo, suggesting that JMJD3 may be the key molecule driving early sepsis progression." (PMID 30337925, 2018).